SOCS3 (suppressor of cytokine signaling 3)
Diseases named in the same sentence as SOCS3 in open-access papers (continued):
Sharing a sentence is not in itself a finding about the gene and the disease.
infection (continued). "The infection significantly increased SOCS3 expression in DMSO-treated NPCs, whereas treatment of MBV or NGIC-I prevented SOCS3 upregulation, indicating pUL97 kinase activity is required for the regulation." (PMID 36753521, 2023). "Furthermore, infection of hepatitis C virus, influenza A virus, respiratory syncytial virus, human immunodeficiency virus, and herpes viruses, induce SOCS3 expression to antagonize STAT1/2 activation, implying SOCS3 can be a therapeutic target for the development of broad-spectrum antiviral drugs." (PMID 36930690, 2023). "SOCS3 is a negative regulator of the JAK2-STAT3 pathway, which plays an important role in inflammation and the response to infection." (PMID 35444649, 2022). "We also show that infection of cells with this virus induces SOCS1 and SOCS3, and that pJAK2 eliminates this induction." (PMID 35799776, 2022). "The expression of SOCS3 in DF-1 cells infected with ALV-J was higher than that of uninfected cells, except at 12 h post-infection (hpi)." (PMID 34568100, 2021). "A biphasic pattern of SOCS mRNA production was observed with early SOCS1 and SOCS3 mRNA upregulation occurring before immediate early virus gene expression followed later by SOCS1 and SOCS3 mRNA upregulation at 3 days post-infection." (PMID 34358000, 2021). "The fact the OLFML3 affected RV-activated SOCS3 expression at late time point (24 h after infection) suggested an indirect or delayed interaction between OLFML3 and SOCS3." (PMID 34686207, 2021). "Out of the four Jak-STAT signaling molecules (suppressor of cytokine signaling 1 [SOCS1], SOCS3, STAT1, and STAT4) analyzed in this study, only the STAT1 gene was significantly upregulated (36 to 48 hpi) in ALI-PRECs following infection with PHEV." (PMID 34935443, 2021). "It was reported that SOCS3 was induced at the very early stage of HSV-1 infection in human amnion cells FL and was accompanied by JAK phosphorylation within 1 h after infection." (PMID 32149091, 2020). "The qRT-PCR results indicated a time-dependent elevation of SOCS1 and SOCS3 mRNA expression levels in response to both MR766 and PRVABC59 infections." (PMID 32120897, 2020). "The results showed that the expression of SOCS3 significantly increased at 12 h, 24 h, and 36 h after infection, and SOCS1 protein levels increased at 36 h after infection, which was consistent with SOCS mRNA results." (PMID 32149091, 2020). "For example, suppressors of cytokine signalling (SOCSs) proteins SOCS3 and SOCS2 belonging to important family of inflammatory response regulators were shown to augment the infection with M. tuberculosis and S. enterica." (PMID 32070192, 2020). "Previous studies have revealed that DHAV-1 CH60 strain infection significantly induces type I and II interferon responses, activates the JAK-STAT signaling pathway, and enhances SOCS3 mRNA levels in the livers of chicken embryos." (PMID 31024559, 2019). "Herpes simplex virus type 1 (HSV-1) induces both SOCS1 and SOCS3 to block type I IFN at early infection stage within 6 h." (PMID 31861450, 2019). "In addition, transcriptome sequencing has revealed that infection of chicken embryo livers with the CH60 strain is associated with enhanced type I and II interferon responses, activated innate immune responses, and abundant expression of cytokine signaling molecules 1 and 3 (SOCS1 and SOCS3)." (PMID 31024559, 2019). "Transcriptional stimulation of host SOCS1 and SOCS3 was also found in skin samples of MDV-infected chickens at 20 and 30 days post-infection." (PMID 31031749, 2019). "Total cellular RNA was extracted at 3, 6, 9, 12, 24, 48, and 72 h after infection, and the abundance of HCV RNA and mRNA levels of the ISGs MX1, SOCS3, IFNβ, and OAS2 were quantified by qRT-PCR." (PMID 31138826, 2019). "Having shown modulation of cytokine signaling by SOCS3-DH, we tested the effect on CD8 T cell differentiation and function in vivo using an adoptive transfer infection model." (PMID 31748225, 2019).
infection (continued). "Of these molecules, RIG-I, MDA5, ATG5, SOCS1, SOCS3, INF-a, ISG15and ISG56 showed differences in expression levels at different time points after DENV-3 or DENV-3 ADE infection." (PMID 29566761, 2018). "In our study, Tyrosine kinase 2 (TYK2, one of the JAKs) and its negative regulators SOCS1, SOCS3 as well as anti-apoptosis genes BCL-XL and PIM1 were differentially regulated by IRF7 during the H6N2 infection." (PMID 30356848, 2018). "In the process of DENV ADE infection, the expression levels of the SOCS1, SOCS3, RIG-1 and ISG56 genes was found to be different (≥2) comparing to the levels during DENV-3 direct infection." (PMID 29566761, 2018). "Infection of IC-21 mouse macrophages or MEFs with SG-MCMV resulted in early, transient stimulation of SOCS1 and SOCS3 mRNA expression compared with medium-treated controls." (PMID 28182772, 2017). "IFN λ and SOCS-1 and SOCS-3 expression were evaluated at 12 h and 24 h following mock, RSV A2, rA2-GC12 and rA2-GC4 infections." (PMID 28671606, 2017). "We also found that at 3 days following infection in IC-21 macrophages, MCMV stimulation of SOCS3 mRNA is significantly reduced by GCV treatment." (PMID 28182772, 2017). "By contrast, infection of murine embryonic fibroblasts (MEFs) with either productive MCMV or UV-inactivated MCMV significantly stimulates SOCS1 and SOCS3 mRNA expression early after infection." (PMID 28182772, 2017). "The infection of cells with oncolytic adenovirus CN305 (AdCN305)-SOCS3 and AdCN305 cell-penetrating peptides-SOCS3 (membrane permeable SOCS3) results in considerable cytotoxicity of liver tumor cells and downregulation of cyclin D1 and Bcl-xL." (PMID 28228755, 2017). "Productive SG-MCMV infection of MEFs produced similar temporal patterns of SOCS1 and SOCS3 mRNA expression to those found in IC-21 cells." (PMID 28182772, 2017). "Herein we characterized the expression of two prominent members of the SOCS family, SOCS1 and SOCS3, during SG-MCMV infection in cell culture models." (PMID 28182772, 2017). "At 36 h post-infection, the qPCRs showed that TNF-α induced IL-6 expression, and higher IL-6 and TNF-α levels were induced by PCV2 when SOCS3 was silenced, compared with control cells." (PMID 27581515, 2016). "Endogenous SOCS3 mRNA and protein expression levels were detected in PCV2-infected PK-15 cells at 24, 48, and 72 h post-infection and compared with those in uninfected cells." (PMID 27581515, 2016). "Both AXL and SOCS3 were up-regulated approximately 2 fold in JFH1 infected cells (minimum 2 passages, 1 week post infection, 90% infectivity), but were surprisingly down-regulated in a stable cell line of Huh-7s harbouring a genotype 2a SGR." (PMID 26313459, 2015). "As expected, Socs3 mRNA levels were reduced in M. tuberculosis-infected Socs3fl/fl LysM cre BMM when compared to controls, and in vitro infection of BMM with M. tuberculosis stimulated STAT3 phosphorylation that was prolonged in Socs3fl/fl LysM cre BMM." (PMID 23853585, 2013). "In contrast, the results show that knocking down SOCS3 or SHP-2 did not increase phospho-STAT3 levels during either psarA or psarA:gp130 infection." (PMID 40188438, 2025). "While there were no changes in the expression of SOCS3 in HRECs over the course of infection, Deer-RECs showed significant downregulation in response to SARS-CoV-2 infection by 24 hpi." (PMID 38189329, 2024). "In contrast to no STAT1 activation in CVB3-infected WT cells, the infection of SOCS3 knockdown cells resulted in strongly elevated p-STAT1." (PMID 39201692, 2024). "Additionally, B. longum and C. sorokiniana improved the antiviral cellular immune response by upregulating SOCS3 and IFN-γ in the pre- and post-infection assays." (PMID 38791551, 2024).
infection (continued). "A combination of B. longum and C. sorokiniana was used to study its effect on the antiviral response in HT-29 by measuring the mRNA levels of IFN-γ, IL-10, SOCS3, STAT1, and STAT2 genes in cells with the combination of B. longum/C. sorokiniana in the pre- and post-infection assays with rotavirus." (PMID 38791551, 2024). "This may indicate that the antiviral response induced by C. sorokiniana in rotavirus-infected cells was mediated by IFN-α and IFN-γ in the pre-infection assays and STAT1/STAT2 in the post-infection assays and regulated by SOCS3 in both assays." (PMID 38791551, 2024). "Taken together, the data indicate that, in the absence of SOCS3, infection leads to a stronger activation of STAT1, resulting in the enhanced expression of ISGs and reduced virus propagation." (PMID 39201692, 2024). "Moreover, the RFX7 phosphorylation level was increased by either UL97-expressing or HCMV-infection in NPCs, suggesting that pUL97 induces RFX7 phosphorylation to drive SOCS3 transcription." (PMID 36753521, 2023). "The dephosphorylation of SOCS3 suggests that Salmonella virulence factors are not directly involved in the inhibition of cytokine signaling during the early infection period in the cecum." (PMID 35846741, 2022). "Immunofluorescence staining was used to co-label SOCS3 and GFAP proteins and it was found that SOCS3 was highly expressed in astrocytes but not in other cells after infection." (PMID 35296090, 2022). "As a results of Western blot analysis, the expression of SOCS3 was detected in MKN28 and MKN74 cells after T-01 infections did not decrease the expression of SOCS3." (PMID 33659045, 2021). "In HEK293T cells, SOCS3 mRNA expression was generally not affected by both Asibi and YF-17D except for a one-time increase in YF-17D infected cells at initial phase of infection (3 hpi)." (PMID 32722523, 2020). "This suggests that infection with the ΔCagPAI mutant does not induce the secretion of the soluble mediator crucial for SOCS3 expression." (PMID 33023610, 2020). "In particular, the level of SOCS3 mRNA significantly increased at 12 h, 24 h, and 36 h after infection compared to the negative control." (PMID 32149091, 2020). "Among them, Cxcl1, Cxcl2, Cxcl3, Cxcl10, IL1b, Socs3, and Mmp14 were overexpressed more than 100-fold compared with the non-infected sample regardless of infection type." (PMID 30858471, 2019). "To test if SOCS3 protein is induced by IL-6 (with or without infection), we pretreated (or not) LNCaP-JAK1 cells with IL-6 (5 ng/mL, 12 h) and subsequently infected or not these cells with EHDV-TAU (moi = 0.5, 48 h)." (PMID 29441069, 2018). "So we think that SOCS3 and the other Jak-STAT pathway genes may together regulate the activity of the organism in infection, which leads this module to be differentially coexpressed." (PMID 28529955, 2017). "The absence of SOCS3 in macrophages has detrimental consequences after infection with Mtb because excessive cytokine production exacerbated inflammation-induced lung pathology." (PMID 29176982, 2017). "Blockage of STAT pathways therefore does not necessarily preclude the induction of SOCS1 and/or SOCS3 by other cellular or viral mechanisms, even at later times of infection." (PMID 28182772, 2017). "In agreement with these mRNA data, immunofluorescent staining of IC-21 macrophages for SOCS1 or SOCS3 revealed robust stimulation of these proteins at 3 hrs following infection with productive MCMV, but not after treatment with UVi-MCMV or media." (PMID 28182772, 2017). "The present in vivo study shows for the first time that after infection with Mtb the absence of macrophage SOCS3 resulted in exacerbated alternative macrophage activation with strikingly increased levels of Fizz1, Ym1, Il4ra, and Arg1." (PMID 29176982, 2017). "At 24 h post-infection, PCV2 infection induced SOCS3 mRNA expression." (PMID 27581515, 2016).
infection (continued). "When HDAC is inhibited, SOCS1 and SOCS3 are acetylated and chromatin is relaxed, permitting virus transcription and replication and anterograde transport and shedding of HSV-1 in a lytic cycle of infection." (PMID 24567732, 2014). "In T cells, SOCS3 expression was essential for a gp130-independent control of infection with M. tuberculosis, but was neither required for the control of infection with attenuated M. bovis BCG nor for M. tuberculosis in BCG-vaccinated mice." (PMID 23853585, 2013). "Taken together the data indicate that in the absence of SOCS-3, infection leads to a stronger activation of STAT1, resulting in enhanced expression of ISGs and reduced virus titers." (PMID 18989459, 2008). "So far, our data suggest that influenza virus-induced transcriptional upregulation of the SOCS-3 gene is not mediated by the autoregulatory action of type I IFNs but is directly induced through accumulation of viral RNA during infection." (PMID 18989459, 2008). "At 24 h pi, SOCS1 protein expression levels were similar following infection with RSV or RSV mutant viruses; however SOCS3 protein expression was significantly (p < 0.05) higher in ΔG virus infected cells compared to WT infected cells, and substantially higher compared to ΔNS/2 virus infected cells." (PMID 18851747, 2008). "Furthermore, the infection data are consistent with the overexpression results, demonstrating that STAT3 activation is reduced when the GBS of SarA is replaced by the GBS of gp130 based on levels of phospho-STAT3 and SOCS3." (PMID 40188438, 2025). "This limited response occurs despite the strong and significant induction of SOCS3, a key negative regulator of inflammation, during the eclipse phase, suggesting a potential suppression of IFN production and/or JAK-STAT signaling during the early stages of infection." (PMID 40934228, 2025). "Although there is a significant increase in transcript levels of the known JAK-STAT negative regulator SOCS3 during infection, which can lead to JAK2 protein degradation, this does not explain the decrease in levels of both JAK2 and STAT1 at the transcript level." (PMID 39194253, 2024). "Regarding the expression of SOCS3, there was an increase in expression over time, without significant difference in the early stages of infection (12 and 24 hpi), with a greater increase in cells infected with the ZIKVMR766 strain at later stages (p < 0.05 in both)." (PMID 37376550, 2023). "Additionally, regarding socs-3 transcripts, these were still significantly higher at 48 h post-infection compared to the non-infected group." (PMID 35328519, 2022). "Furthermore, the frequencies of the MX1+ ACE2− and SOCS3+ ACE2− cells were not affected by infection, but were significantly affected by age, and were highly accumulated in the lung tissues of both healthy and infected old RMs." (PMID 34471088, 2021). "Moreover, genes such as Ifr9, Ifr8, Ifr7, CSF2RA, STAT1, and STAT2 were expressed to a greater extent in the PmQ infection group than PmCQ2, and Il22, Il6, Nos2, Ccl4, Ccl5, Ifr1, Socs1, and Socs3 were increased only in PmQ infected chickens rather than PmCQ2." (PMID 32851030, 2020). "However, markedly reduced induction of SOCS3 was shown at late stage of the infection (12 hpi), implying that de novo synthesized proteins were required for efficient SOCS3 expression at late stage but not for early stage of IAV infection." (PMID 31474976, 2019). "Compared to the corresponding protein level measured in uninfected cellular extracts, the infection performed with P. gingivalis at a MOI of 100 significantly reduced the expression level of SOCS-3 (5-fold), IRF-1 (5-fold), and EGFR (6-fold), but not STAT-3, in the nuclear extracts." (PMID 28748038, 2017). "Having shown that in the absence of macrophage SOCS3 Mtb evades in early appearing Arg1-expressing cells, we next analyzed the fate of mycobacteria in different types of macrophages during the course of infection in vivo." (PMID 29176982, 2017).
infection (continued). "Infection with BCG activates Wnt/β-catenin signaling, resulting in the expression of a host of genetic signatures important for subsequent regulatory responses, including cyclooxygenase (COX)-2, suppressor of cytokine signaling-3 (SOCS-3), and Jagged1 (ligand for Notch1 signaling)." (PMID 28018344, 2016). "Moreover, γδ+ T cells impaired the transfer of protection by Socs3fl/fl lck cre CD4+T cells, suggesting that SOCS3 inhibits a non-redundant detrimental role of γδ+ T cells in the outcome of infection with M. tuberculosis." (PMID 23853585, 2013). "Meanwhile, anti-inflammatory factors such as TNFAIP3, NFKBIA, NFKBIZ, SOCS1, SOCS3, and IL-10 were elevated, with the reverse trends for the inflammation-inducing genes PPBP and MARCO at 38 hpi, suggesting that the pro- and anti-inflammatory responses might coexist in PAMs during YC-2020 infection." (PMID 36338035, 2022). "Thus, we generated A549 cell lines stably expressing shRNAs specifically targeting IL-6 receptor subunits glycoprotein 130 (gp130) or IL-6Ra and found that knockdown of IL-6 receptor subunits did not affect the mRNA levels of SOCS3 at early stage of the infection." (PMID 31474976, 2019). "Unlike UVi-MCMV infection of IC-21 cells, which produced no significant up-regulation of SOCS1 or SOCS3 transcripts during the time points observed in these macrophages, UVi-MCMV infection of MEFs caused significant, albeit transient, stimulation of SOCS1 and SOCS3 mRNA expression at 2 hpi." (PMID 28182772, 2017). "FhTeg-induced expression of SOCS3 was reversed upon pre-incubation of DCs with GalNAc-4S, however this did not reverse the immune modulatory properties of FhTeg suggesting that SOCS3 despite been induced during infection may not be important to its immune modulatory properties." (PMID 27104959, 2016). "However, Julien and coworkers have observed that up-regulation of SOCS-1 and SOCS-3 in IAV-infected cells is IFNAR1-dependent, which does not contradict with our observation, because we found that the culture supernatants at the later stages of infection indeed stimulated SOCS-1 expression." (PMID 24391501, 2014). "Infection of the UV-inactivated DENV, a virus able to bind and enter cells but unable to replicate, failed to increase SOCS3 expression in cells, indicating the essential role of DENV replication in SOCS3 induction." (PMID 36930690, 2023). "Type I IFN, SOCS-1 and SOCS-3 expression were not detectably different between RSV A2 and RSV mutant infection, but type III IFN secretion was increased in rA2-GC12 and GC4 infected Calu-3 cells." (PMID 28671606, 2017). "We found that SOCS1 and SOCS3, but not SOCS5, mRNA transcripts are up-regulated at early time points following infection of IC-21 monolayers with SG-MCMV." (PMID 28182772, 2017). "Yet, after infection with Mtb the expression of Nos2 and the production of RNI were rather elevated in the absence of macrophage SOCS3." (PMID 29176982, 2017). "That SOCS3, but not SOCS1, is sensitive to GCV treatment suggests divergent or temporally-driven mechanisms for stimulation of these proteins during late infection with MCMV." (PMID 28182772, 2017). "In the liver, FoxO3a−/− mice had significantly reduced expression of various cytokines such as IL-1β, IL-12, TNF and IFN-γ at day 7 post-infection as measured by qRT-PCR; though the expression of SOCS-1 and SOCS-3 were not altered." (PMID 27599659, 2016). "In these studies, the role of SOCS1 and SOCS3 negative regulation of the type I IFN response and ISG15 expression were evaluated after infection of MLE-15 cells with RSV or RSV mutant viruses lacking the G gene, or having NS1 and NS2 gene deletions." (PMID 18851747, 2008). "The studies center on SOCS1 and SOCS3 negative regulation of the type I IFN response and ISG15 expression following infection with RSV or RSV mutant viruses lacking the G gene, or NS1 and NS2 gene deletions." (PMID 18851747, 2008).